EGFR (epidermal growth factor receptor)
Diseases named in the same sentence as EGFR in open-access papers (continued):
Sharing a sentence is not in itself a finding about the gene and the disease.
bladder cancer (continued). "MiR-200 overexpression in bladder cancer cells increases their sensitivity towards the epidermal growth factor receptor (EGFR) inhibitors via regulating the expression of ERBB receptor feedback inhibitor 1 (ERRF1)." (PMID 36685879, 2022). "In vitro inhibition of EGFR modulates RON activity in bladder cancer cell lines demonstrating the interplay between these two RTKs." (PMID 35454943, 2022). "The EGFR-targeted bladder cancer therapies have been reported to yield mixed results with regards to their cancer-killing efficacy." (PMID 36575233, 2022). "The EGF/EGFR ligand/receptor couple is frequently overexpressed in bladder cancers, with squamous bladder cancers qualified as being EGFR-addicted." (PMID 35740379, 2022). "We demonstrate for the first time a critical role for HOTAIR and identify the involvement of the EGFR-ProT-NF-κB-HOTAIR signaling axis in cisplatin-induced cachexia in bladder cancer and likely other cancers." (PMID 36471329, 2022). "The anti-tumor activity of hypericin PDT in combination with Erbitux (an angiogenesis inhibitor), which acts on the epidermal growth factor receptor (EGFR) in human bladder cancer cells, was investigated." (PMID 35163996, 2022). "In the current study, we show that cisplatin induces EGFR activation, thereby resulting in ProT overexpression in bladder cancer cells." (PMID 36471329, 2022). "EGFR is the most promising target molecule since it is overexpressed in 55–74% of bladder cancer tissues." (PMID 35740662, 2022). "EGFR-targeted NIR-PIT provokes cancer cell death in EGFR-expressing human bladder cancer cells in vitro and suppresses tumor growth in mice xenografts from the same cell lines." (PMID 35740662, 2022). "After performing a series of bioinformatic and machine learning approaches, we identified distinct tumor microenvironment clusters and three bladder cancer specific immune-related genes (EGFR, OAS1 and MST1R)." (PMID 36267410, 2022). "EGFR-targeted NIR-PIT was also effective for EGFR-expressing canine bladder cancer cells both in vitro and in vivo." (PMID 35740662, 2022). "Next, levels of phospho-EGFR, EGFR, phospho-NF-κB, and NF-κB were examined by immunoblot analysis in human bladder cancer cells treated with cisplatin." (PMID 36471329, 2022). "Here, we studied the in vitro effects of cetuximab monoclonal antibodies (mAbs) targeting EGFR on the bladder cancer cells and role of CD46." (PMID 36575233, 2022). "Cooperation between RON and EGFR has been previously reported in bladder cancer as they are co-expressed in one third of patients." (PMID 35454943, 2022). "Taken together, these results indicate that cisplatin can upregulate the expression of ProT and HOTAIR and that activation of EGFR and NF-κB participates in this pathway in bladder cancer cells." (PMID 36471329, 2022). "In the current study, we demonstrate that cisplatin treatment induces EGFR activation in bladder cancer cells, resulting in the upregulation of the ProT-NF-κB-HOTAIR axis and leading to promoting cachexia-associated pro-inflammatory cytokine expression." (PMID 36471329, 2022). "EphA2 is the key mediator of progranulin signaling in bladder cancer where progranulin did also modestly activate EGFR, EphA4 and EphB2." (PMID 36471440, 2022). "Epidermal growth factor receptor (EGFR), another receptor tyrosine kinase, shows overexpression in up to 74% of bladder cancer specimens, as compared to the relatively low expression level seen in normal urothelium." (PMID 35326708, 2022). "EGFR is also overexpressed in bladder cancer and shown to be related to tumor stage, progression and clinical results." (PMID 34867408, 2021). "In accordance with our observations, a previous study showed that dual inhibition of EGFR and p38 had a synergistic inhibitory effect on the proliferation of bladder cancer cell lines." (PMID 34943871, 2021).
bladder cancer (continued). "EGFR has been previously shown to be enriched in basal-like bladder cancer, and some groups of muscle invasive bladder cancers have been determined to respond to EGFR inhibitors." (PMID 35068946, 2021). "In one of our studies, epidermal growth factor receptor (EGFR)-ERK signaling activation by AR in bladder cancer cells has also been documented." (PMID 33652650, 2021). "Another study also revealed that upregulation of miR-490-5p led to decreased EGFR expression, hampering cell invasion in bladder cancer cells." (PMID 34702201, 2021). "Compound 1 was also found to be involved with Akt, mTOR, and MEK-ERK pathways in renal carcinoma cells or the inactivation of EGFR-related pathways in bladder cancer cells." (PMID 34641476, 2021). "EGFR is overexpressed in several tumor types, including head and neck, breast, renal, non-small cell lung, colorectal, ovarian, pancreatic, and bladder cancers, thus triggering an early interest in EGFR-targeting therapies." (PMID 33672373, 2021). "The role of EGFR as a strong independent prognostic marker and therapeutic target in bladder cancer has been well identified." (PMID 33842349, 2021). "Conversely, ectopic expression of miR-200 reverses the resistance of bladder cancer cells to EGFR inhibition therapy by regulating EMT." (PMID 34206547, 2021). "EGFR can be used as a potential therapeutic target for muscle-invasive bladder cancer presenting a basal-like phenotype." (PMID 33962639, 2021). "On the other hand, EDIL3 (EGFR-activating, proangiogenic integrin ligand) was previously identified in exosomes from invasive bladder cancer cell lines and from urine of patients with high-grade UBC." (PMID 34202855, 2021). "The expression of EGFR in OSCC cells is elevated compared with that in colorectal or bladder cancer." (PMID 33449240, 2021). "In vitro and in vivo experiments utilizing the EGFR/HER2 double-positive bladder cancer cell line SW-780 showed more potent effects upon combinatorial treatment in comparison to mono treatments." (PMID 34123841, 2021). "In vitro, Panitumumab-IR700 showed cytotoxic effects on EGFR-positive bladder cancer cells in a dose-dependent manner." (PMID 34123841, 2021). "In a subsequent study in 2015, the same group showed that application of even higher radiation doses did not lead to toxic side effects after instillation of 213Bi-Anti-EGFR-mAb in bladder cancer-bearing xenografts." (PMID 34123841, 2021). "For instance, epidermal growth factor receptor, urinary glycoprotein and α6β4 integrin are highly expressed in bladder cancer." (PMID 34867408, 2021). "Overexpression of EGFR, ERBB2 or ERBB3 is associated with tumor grade, stage, and prognosis in bladder cancer." (PMID 34094968, 2021). "Next, potential integrated prognosis-related proteins (IPRPs) model (including BECLIN, PKCALPHA, EGFR, ANNEXIN1, AXL and SRC) was constructed to assess the survival risk score of bladder cancer." (PMID 33830879, 2021). "Promotion: Studies show that ARs increase the protein level and activity of the epidermal growth factor receptor (EGFR) as well as Herb2, promoting the development and progression of bladder cancer through the EGFR / ERBB2 pathway." (PMID 33919565, 2021). "EGFR has been reported to be upregulated on the surface of tumour cells of glioblastoma, lung cancer, head and neck cancer, and bladder cancer." (PMID 33737524, 2021). "Estrogen receptor alpha (ERα) was shown to play a protective role in bladder cancer through circ_0023642/miR-490-5p/EGFR signaling." (PMID 32629427, 2020). "Cytoprotective autophagy has been observed in mutant and wild-type EGFR NSCLC and in EGFR mutant bladder cancer." (PMID 32878084, 2020). "Functionally, we confirmed a central role of wild-type EGFR in squamous-differentiated bladder cancer cells, as they are vulnerable to perturbances of the ERBB signaling pathway in vitro." (PMID 32978523, 2020).
bladder cancer (continued). "Gene functional enrichment analysis revealed that the main mechanisms were involved in carcinogenesis, including bladder cancer, EGFR tyrosine kinase inhibitor resistance, and platinum drug resistance." (PMID 32190662, 2020). "Oral genistein given 14–21 days before urothelial bladder cancer surgery was well-tolerated and reduced bladder cancer tissue phosphorylated-epidermal growth factor receptor (EGFR), which contributes to the proliferation and survival of cancer cells." (PMID 33185690, 2020). "In 2014, Rebouissou and colleagues suggested the basal-like bladder cancer subgroup to be sensitive for anti-EGFR treatment." (PMID 32978523, 2020). "For basal or squamous-like bladder cancer, molecular signatures were found based on clustering RNA-seq data, including EGFR." (PMID 33334367, 2020). "These multifunctional nanoparticles showed an enhanced uptake into EGFR-overexpressing T24 bladder cancer cells through receptor-mediated cellular internalization." (PMID 32498278, 2020). "Overexpression of epidermal growth factor receptor (EGFR) is common in solid tumours, including breast, lung, prostate, and bladder cancer." (PMID 32872665, 2020). "Our TMA in human bladder cancer samples also confirmed this observation, where we found co-expression of both in 45.2% of the samples with varying levels of EGFR and HER2 staining." (PMID 30765854, 2019). "The average gene expression in the TCGA provisional dataset confirmed that EGFR is elevated in bladder cancer and specifically in the ‘basal’ subtype classes 3 and 4 (p < 0.01, ANOVA)." (PMID 30765854, 2019). "Previously, we have shown that the basal/squamous subtype of bladder cancer, with enrichment in EGFR expression, can be very effectively targeted using EGFR-directed PIT6." (PMID 30765854, 2019). "In conclusion, the use of EGFR and HER2 as co-targets for PIT expands on our previous work of targeting EGFR-enriched bladder cancer." (PMID 30765854, 2019). "EGFR overexpression is seen in up to 74% of bladder cancer tissue specimens, with a relatively low expression seen in normal urothelium." (PMID 30765854, 2019). "A total of 232 bladder cancer samples were stained for EGFR and HER2, with 186 (80.1%) samples showing staining for either EGFR or HER2 or both." (PMID 30765854, 2019). "Overexpression of the epidermal growth factor receptor (EGFR) has been documented in several malignancies including bladder cancer and glioma." (PMID 31165773, 2019). "Taking advantage of the high molecular heterogeneity in bladder cancer, we targeted cancer that expresses both cell-surface EGFR and HER2." (PMID 30765854, 2019). "In the case of bladder cancer, epithelial growth factor receptor (EGFR) is overexpressed in more than 70% of bladder cancer tissue, but has a low expression in normal tissue, and UMUC3 cells also overexpress EGFR." (PMID 31357730, 2019). "In an animal model of human bladder cancer 213Bi-anti-EGFR immunoconjugates showed effective eradication of human EJ28Luc tumor cells and therefore significantly prolonged overall survival of the treated animals." (PMID 31165773, 2019). "The EGFR protein is related to the type 1 tyrosine kinase receptor family and is important for the progression of bladder cancer." (PMID 31480265, 2019). "In our previous work, we showed that metformin and gefitinib cooperatively inhibited bladder cancer growth by inhibiting EGFR signaling." (PMID 30053908, 2018). "Anti-epidermal growth factor receptor (EGFR) antibody therapy is used in EGFR expressing cancers including lung, colon, head and neck, and bladder cancers, however results have been modest." (PMID 29721181, 2018). "In a previous study, we showed that the combination of metformin and the epidermal growth factor receptor (EGFR) inhibitor gefitinib produces cytotoxic effects in bladder cancer cells." (PMID 30053908, 2018).
bladder cancer (continued). "The EJ human bladder cancer cells were used as a model for evaluating the therapeutic efficacy and biodistribution of the EGFR-targeted MNT." (PMID 30510514, 2018). "We were able to validate the presence of a substantial amount of EGFR on six bladder cancer cell lines." (PMID 29456764, 2018). "Results of most of the literature revealed that more than half of cases of bladder cancer overexpresses EGFR." (PMID 29879970, 2018). "In this study, we aim to manufacture anti-EGFR indocyanine green (ICG) mitomycin C (MMC) encapsulated perfluorocarbon double nanoemulsions (EIMPDNEs), and explore their photochemotherapeutic efficacy on EGFR-expressing bladder cancer cells in vitro." (PMID 29701711, 2018). "In this paper, we have presented a proof-of-concept study of targeted photochemotherapeutics for EGFR-expressing bladder cancer cells using developed EIMPDNEs." (PMID 29701711, 2018). "In the present study, we assessed EGFr signaling in the normal urothelium and in bladder cancer by letting normal and malignant cells grow in conventional cell cultures and in three-dimensional cell cultures." (PMID 29508172, 2018). "In the current study, we evaluated EGFR expression in bladder cancers of locoregional population and found EGFR expression in 46% cases of bladder cancer." (PMID 29879970, 2018). "All investigated bladder cancer cell lines demonstrate significant enhancement of 111In cytotoxicity after its attachment to EGFR-targeted MNT." (PMID 30510514, 2018). "With the merits of improved ICG stability, EGFR binding specificity, and effective cancer cell eradication, the EIMPDNEs exhibit potential for use in EGFR-expressing bladder cancer therapy with lower chemotoxicity." (PMID 29701711, 2018). "The objective of this study was to evaluate the in vitro and in vivo efficacy of 111In attached MNTs to kill human bladder cancer cells overexpressing epidermal growth factor receptor (EGFR)." (PMID 30510514, 2018). "Due to the prevalence of EGFR expression in bladder cancer cells, EGFR-target noninvasive therapeutics have been recognized as a viable approach for treatment, and consequently have been widely studied in the past decade." (PMID 29701711, 2018). "Intravesical application of targeting EGFR 213Bi α-particle emitter containing immunoconjugate showed promising results in early tumor stages using mouse in situ human bladder cancer xenografts." (PMID 30510514, 2018). "The normal urothelium generally lacks any noticeable EGFR expression, but the most common type of urinary bladder cancer, transitional cell carcinoma, in most cases is characterized by expression of this receptor in the superficial layer." (PMID 30510514, 2018). "We also observed that concurrent autophagy inhibition significantly enhanced the anti-clonal proliferation effects of EGFR inhibitors in T24 and J82 bladder cancer cells (respectively)." (PMID 28165387, 2017). "It has been reported that patients with bladder carcinoma expressed EGFR and high expression correlated with poor prognosis." (PMID 28642617, 2017). "The EGFR inhibitors, lapatinib and gefitinib, were evaluated for anti-cancer effects on T24 human bladder cancer cells." (PMID 28165387, 2017). "To our knowledge, we are the first to report evidence that concurrent treatments of EGFR and autophagy inhibitors can significantly enhance the limited efficacy of EGFR inhibitors in human bladder cancer cells in vitro." (PMID 28165387, 2017). "In the current studies, we identify a novel function of BIR domains in the promotion of bladder cancer cell growth by upregulation of EGFR expression." (PMID 28057023, 2017). "Our study revealed that the synergistic growth inhibitory action between EGFR inhibitors and autophagy inhibitors was induced via apoptotic cell death in human bladder cancer cells." (PMID 28165387, 2017).
bladder cancer (continued). "Second, to better address the clinical impact, the phenomenon of autophagy activation by EGFR inhibitors treatments should be examined in human bladder cancer specimens by using patient-derived bladder cancer xenograft models." (PMID 28165387, 2017). "In summary, EGFR inhibitors significantly induced autophagy activities in human bladder cancer cells, and concomitant suppression of autophagy activities enhanced the anti-cancer effects of EGFR inhibitors, such as lapatinib and gefitinib." (PMID 28165387, 2017). "In summary, concomitant inhibition of autophagy activities potentiated the anti-cancer effects of EGFR inhibitors in human bladder cancer cells, indicating a novel therapeutic strategy to treat advanced bladder cancer." (PMID 28165387, 2017). "This is the first demonstration that XIAP promotes the anchorage-independent growth of human bladder cancer cell via positive regulation of EGFR translation." (PMID 28057023, 2017). "We demonstrate here that XIAP is a strong positive regulator of EGFR expression in human bladder cancers and that XIAP BIR domain plays an important role in the mediation of EGFR protein expression by promoting its protein translation." (PMID 28057023, 2017). "This is the first demonstration of XIAP BIR domains as a potent positive regulator of EGFR expression, which in turn promotes bladder cancer cell anchorage-independent growth." (PMID 28057023, 2017). "EGFR and IL6 are upstream regulators of STAT3, and all have been implicated in basal breast and bladder cancers." (PMID 27845906, 2016). "Aberrant EGFR signaling plays an important role in the tumorigenesis, migration, apoptosis resistance and stromal invasion of bladder cancer." (PMID 27870887, 2016). "Epidermal growth factor receptor (EGFR) has been reported to be highly expressed in Bladder cancers." (PMID 27447744, 2016). "The level of EGFR expression directly correlates with tumor grade, stage, and survival in human bladder cancer, thus serving as a novel prognostic marker to predict the chemo-responsiveness of patients with locally recurrent or metastatic MIBC." (PMID 27438149, 2016). "Elevated EGFR is common in primary bladder cancers with about 50% of cases exhibiting overexpression." (PMID 26930657, 2016). "We combined metformin with Gefitinib, attempting to suppress bladder cancer through targeting metabolism and EGFR signaling pathway." (PMID 27334428, 2016). "First, bladder cancers express high levels of EGFR, where local release of EGFR ligands would promote bladder cancer growth." (PMID 26930657, 2016). "Activation of the EGFR signal pathway reduces TNF-α-related apoptosis-inducing ligand-induced apoptosis through AKT- and XIAP-dependent mechanisms in EGFR-dependent human bladder cancer cells." (PMID 26160843, 2015). "MiR-200 family appears to control the EMT process and sensitivity to EGFR therapy in bladder cancer cells." (PMID 25991007, 2015). "Accordingly, the efficacy of targeted therapy directed at EGFR signals has been assessed in bladder cancer." (PMID 26770009, 2015). "Altered expression of EGF family members (e.g. EGF, epiregulin and HB-EGF (heparin-binding epidermal growth factor-like growth factor)) and EGFR has been suggested as mediators of bladder cancer progression." (PMID 26250800, 2015). "In an earlier study we have also demonstrated that targeting EGFR using cetuximab improved the efficacy of PDT treatment in a human bladder cancer model." (PMID 25918252, 2015). "EGFR is widely reported to be a molecular marker expressed in bladder cancer, and upregulated EGFR signaling is known to be a poor prognostic predictor." (PMID 26090723, 2015).